NELL1 (neural EGFL like 1)
Diseases named in the same sentence as NELL1 in open-access papers (continued):
Sharing a sentence is not in itself a finding about the gene and the disease.
NELL1 also shares sentences with these, for which no sentence is quoted: neurological disorders (3 papers); Autoimmunity (2); esophageal adenocarcinoma (2); Anxiety (1); autism (1); cervical cancer (1); cleidocranial dysplasia (1); colorectal cancer (1); deafness (1); delirium (1); depression (1); embryonal rhabdomyosarcoma (1); endometrial carcinoma (1); fibrosis (1); follicular lymphoma (1); glioblastoma (1); Hepatitis (1); IgA nephropathy (1); immune disease (1); infection (1); infertile (1); invasive ductal carcinoma of the breast (1); lung adenocarcinoma (1); mixed connective tissue disease (1); nephrotic syndrome (1); neuroblastoma (1); nicotine dependence (1); Obesity (1); renal cell carcinoma (1); systemic lupus erythematosus (1).